CD4 (CD4 molecule)
Diseases named in the same sentence as CD4 in open-access papers (continued):
Sharing a sentence is not in itself a finding about the gene and the disease.
meningoencephalitis (18 papers, 2008 to 2025). Inflammation of the meninges and brain, generally secondary to an infectious cause. "Specifically, these new ADRs include fat redistribution, HIV-associated neurocognitive disorders, meningoencephalitis, and elevated CD4 lymphocyte counts." (PMID 39697536, 2024). "In previous work, we have shown that C3H/He mice are susceptible to acute phase-restricted meningoencephalitis and rare CD4+ and CD8+ cells are detected in the CNS of chronically infected mice." (PMID 25695249, 2015). "Cases of meningoencephalitis were associated with increasedinfiltration of both CD4+ and CD8+ T cells." (PMID 18615183, 2008). "In our present study, the patients with higher CD4 T cell count were shown with more obvious leptomeningitis or meningoencephalitis, indicating a good response to infection of C. neoformans." (PMID 26871791, 2016). "Clinical Aβ vaccination trial AN1792 was interrupted due to the development in 6 % of the patients of meningoencephalitis likely involving pro-inflammatory CD4+ T cells." (PMID 25982697, 2015). "The development of meningoencephalitis in some AD patients following Aβ vaccination (AN1792) was sought to involve pro-inflammatory CD4+ T cells." (PMID 25982697, 2015). "A large number of CD3+ and CD4+ T cells had infiltrated into the brains of MOG-induced or Aβ42-induced EAE mice, possibly causing meningoencephalitis." (PMID 24987466, 2014). "Case 5 the present case had a moderately low CD4+ T-lymphocyte count and had rapid progression to a meningoencephalitis." (PMID 21118561, 2010). "The fatal outcome was likely related to delayed diagnosis and treatment, severe immunosuppression (CD4 = 39 cells/mm3), high viral load (94,638 copies/mL), and the involvement of TcI, which has been consistently associated with fatal RCD-related meningoencephalitis." (PMID 41172398, 2025). "However, it is generally believed that CD4+ Th1 cells triggered the development of meningoencephalitis following Aβimmunization." (PMID 18615183, 2008). "Summing up, we found a clear link between intrathecal CXCL13 elevations and CXCR5+CD4 T cells in particular in meningoencephalitis patients and CXCR5+CD4 T cell correlating with B cell frequencies in neuroimmunological disorders." (PMID 34446066, 2021). "Thus, inappropriate boosting of endogenous naturally occurring Aβ-specific CD4+ T cell responses, e.g. through vaccination in the presence of a Th1 adjuvant, may likely be involved in the development of meningoencephalitis in selected AN1792 patients displaying given MHC haplotypes." (PMID 25982697, 2015). "In recent studies we showed that mice infected with Tacaribe virus develop a meningoencephalitis that is driven by the CD4+ and CD8+ T cell response to the virus as mice lacking T cells do not develop disease despite high levels of virus in the CNS." (PMID 27855206, 2016). "Immunization of F1 SJLxB6 amyloid precursor protein (APP) transgenic (APP-Tg) AD mice with dominant T cell epitope Aβ10-24 stimulated peripheral CD4+ T cell responses but did not result in T cell infiltration nor the occurrence of meningoencephalitis." (PMID 25982697, 2015). "The potential role of the recently described CD4+Th17 cells in the production of meningoencephalitis has not been evaluated." (PMID 18615183, 2008). "Finally, in Cambodia, among a subgroup of 295 patients—most of whom had a CD4 count below 100 cells/μL but none of whom had signs of meningoencephalitis—10.8% were positive." (PMID 24476751, 2014). "Vaccination with such epitopes in the absence of concomitant Aβ-specific humoral nor CD4+ T cell responses was used to analyze the migration of CD8+ T cells into the brain parenchyma of APPPS1 mice, and their potential role in the induction of meningoencephalitis and/or neuronal damage." (PMID 25982697, 2015).
oral cancer (18 papers, 2014 to 2024). "It is also found that in patients with oral cancer the circulating or tumor infiltrating CD8+ T cells are more susceptible to apoptosis than the CD4+ T cells." (PMID 24465587, 2014). "CD4+ T-helper cell counts were lower in oral cancer patients compared to healthy controls, suggesting potential immune dysregulation." (PMID 39456670, 2024). "Recently, a study confirmed that tumor-infiltrated memory CD4 + T cells correlate with better prognosis in patients with oral cancer." (PMID 37221555, 2023). "Because of the different consequences of CD4 + T cells in tumors, most studies didn’t focus on targeting these cells for oral cancer therapy." (PMID 37221555, 2023). "In the present study, we also confirmed that this oral cancer vaccine and B. longum itself significantly increased the number of CD4+ T cells in MLN." (PMID 34589578, 2021). "The tobacco-related oral cancer is likely to be connected with multiple systemic immune impairs, especially defected CD4+ and CD3+ T cells and a differential regulation of IL-4 and IL-2 in CD8+ and CD4+ T-cell subsets in the peripheral blood." (PMID 31582940, 2019). "As lesions advanced to oral cancer, CD4+ cell levels declined in the wildtype mice, while levels in the IL-23R KO mice remained constant." (PMID 29664967, 2018). "In this study, the presence of circulating Tregs in 39 oral cancer patients and 24 healthy donors was examined by studying the presence of the CD4+CD25hiCD127low cell population in their peripheral blood mononuclear cells using flow cytometry." (PMID 25153698, 2014). "Additionally, we observed the downregulation of specific metabolites, including SCFAs and CD4+T-helper cell counts, in oral cancer." (PMID 39456670, 2024). "Similarly, the downregulation of CD4+ T cells in oral cancer suggests a significant mechanism of immune suppression, highlighting the potential for targeting both T cell pathways and microbiome interactions in therapeutic interventions." (PMID 39456670, 2024). "In addition, in the peripheral circulation of patients with oral cancer, a pronounced CD4+ T lymphocyte exhaustion was noticed, especially in the advanced stages of the disease." (PMID 35206956, 2022). "Furthermore, patients who were at early stages of oral cancer had higher levels CD4+CD25hiCD127low regulatory T cells (p = 0.027) but this correlation was not seen for the CD8+ T cells/Tregs ratio." (PMID 25153698, 2014). "The CD4/CD8 ratio was associated with tumor recurrence but not OS in 52 patients with oral cancer." (PMID 30153850, 2018). "Oral cancer tissues showed significantly elevated levels of the CPT1A protein; an increased presence of T-helper cell counts (CD4+); and higher levels of OXSR1, IL-6, and TNF-α." (PMID 39456670, 2024). "In both tumor-bearing mice and oral cancer patients, heat therapy results in elevated lymphocyte transformation index (LTI), CD4+ cell counts, and significantly increased levels of interleukin-2 (IL-2) and tumor necrosis factor-α (TNF-α) activity." (PMID 39027362, 2024). "Calnexin or CANX is an ER stress chaperone transmembrane protein involved in glycoprotein folding, is considered a prognostic indicator and therapeutic target in CRC, and is found to restrict antitumor CD4+ and CD8+ T cells in oral cancer." (PMID 36033825, 2022). "Patients with oral cancer exhibited notable changes in enzymes critical for fatty acid metabolism, particularly CPT1A, while healthy controls had higher levels of short-chain fatty acids (SCFAs) and CD4+T-helper cell counts." (PMID 39456670, 2024). "Moreover, low levels of CD4+ and CD8+ lymphocytes have been found in patients with oral cancer with active disease, thus suggesting a decreased function of effector cells." (PMID 34439365, 2021). "Indeed, our CD4 and CD8 depletion study revealed that the efficacy of this oral cancer vaccine greatly relies on the function of both CD4+ and CD8+ T cells." (PMID 34589578, 2021).
polymyositis (18 papers, 2007 to 2025). A rare idiopathic inflammatory myopathy characterized by symmetric proximal muscle weakness and elevated muscle enzymes. "In another study, a patient with polymyositis showed significantly elevated expression of CD3+ CD4+ HLA-DR+ cells in heparinized whole blood samples." (PMID 34399738, 2021). "The resulting histopathologic abnormalities resembled some features of human polymyositis including CD4+ and CD8+ T cell infiltration." (PMID 25161767, 2014). "In one study, using three dogs, CD4+ T-cells were found in excess of CD8+ T-cells which advocates a divergent aetiology to other cases of canine polymyositis." (PMID 23457575, 2013). "Given the previous observation of CD4+ T-cells being found in excess CD8+ T-cells in Hungarian Vizsla polymyositis biopsies, it would be particularly interesting to see if there are comparisons with canine masticatory muscle myositis, a disease where this is also a feature." (PMID 23457575, 2013). "The pathogenesis involves an attack of B lymphocytes, macrophages, and CD4+ T lymphocytes in the muscle capillaries, while polymyositis (PM), which is more common in adults, involves a large degree of focal muscle fiber destruction by CD8+ T lymphocytes." (PMID 39336498, 2024). "In humans, the presentation of IIM includes the excessive activation of tissue-infiltrating CD8+ and CD4+ T cells and the increased expression of MHC class I in patients with polymyositis." (PMID 39810259, 2025). "Specifically, polymyositis demonstrated the capacity to decrease the levels of 2 immune cell types (OR < 1, P < .05): B cell panel: CD28 on secreting CD4 regulatory T cell and myeloid cell panel: CD45 on CD33‐ HLA-DR‐." (PMID 39470507, 2024). "The histopathological characteristics of polymyositis are mononuclear inflammatory cell infiltration, mainly the CD8+ cytotoxic T cells and CD4+ T cells." (PMID 36538023, 2023). "Immunological studies demonstrate high CD4 T lymphocyte and CD4/CD8 ratio in sarcoid myopathies, whereas there is CD8 T-lymphocyte predominance in polymyositis and in inclusion body myositis." (PMID 23691415, 2013). "Unlike polymyositis, in which CD8+ T cells are the predominant infiltrating immune cells, dermatomyositis muscle biopsy is mainly invaded by B cells, macrophages, dendritic cells and CD4+ T cells." (PMID 36538023, 2023).
primary biliary cholangitis (18 papers, 2000 to 2026). Primary biliary cholangitis (PBC) is a chronic and slowly progressive cholestatic liver disease of autoimmune etiology characterized by injury of the intrahepatic bile ducts that may eventually lead to liver failure. "Recently, high-expression of XIST in CD4-positive cells and natural killer cells has been suggested to trigger the proliferation of naïve CD4 (+) T cells in primary biliary cholangitis." (PMID 38265097, 2024). "The destruction of bile ducts in primary biliary cirrhosis, primary sclerosing cholangitis and liver allograft rejection seems to be related to cell-mediated immunological attack by cytotoxic T lymphocytes of either CD4 or CD8 phenotype." (PMID 11018850, 2000). "However, the high expression of XIST has been shown to be associated with primary biliary cholangitis in females, XIST can stimulate the proliferation and differentiation of initial CD4+ T cells, which considered to be the reason for the high incidence of PBC in females." (PMID 39346946, 2024). "In patients with primary biliary cholangitis (PBC), the levels of CD4+CXCR5+CD127loCD25hi Tfr cells, as well as CCR7hiPD-1lo central memory Tfr cells, are dramatically decreased, whereas those of CCR7loPD-1hi effector memory Tfr cells are increased." (PMID 32676074, 2020). "In primary biliary cholangitis (PBC), PD-1-targeted CAR-T cells deplete CD4 T cells, reducing biliary epithelial cytotoxicity in mice." (PMID 41357209, 2025). "Portal tract infiltration with CD3+, CD4+, and CD8+ lymphocytes results in chronic nonsuppurative destructive cholangitis and epithelioid granuloma formations." (PMID 22007316, 2012). "It is reported that a direct role for CD4+CD25+ Treg cells in restraining B cell autoantibody production and defects in CD4+CD25+ Treg cells may be crucial to the development of primary biliary cirrhosis." (PMID 24672784, 2014). "Interestingly, in primary biliary cirrhosis patients, GWAS have identified both the Hedgehog pathway genes and MHCII genes, supporting the idea that the influence of Shh on MHCII expression in the thymus might be important for central tolerance of the CD4 population." (PMID 26778835, 2016).
alcoholism (17 papers, 2013 to 2023). "Interestingly, our results indicated that the carcinogenic effects of memory activated CD4 T cells and M2 macrophages may be further amplified in alcohol-related HCC." (PMID 34646769, 2021). "Furthermore, our study indicated that M2 macrophages, CD4+ T cells, NK cells, B cells and monocytes may participated in the development of alcohol-related HCC, which may involve the activation of STAT3 and NF-kB transcription factors or the accumulation of ROS and iron." (PMID 34646769, 2021). "In summary, chronic alcohol leads to mesenteric lymphatic leakage, DC leakage into PLAT, Treg expansion in PLAT, decreased CD4/CD8 ratio in the MLNs, and decreased glucose uptake by PLAT." (PMID 31443389, 2019). "The CD4 count was only measured on those in the ART programme, and so there was insufficient CD4 data to assess whether there was more advanced HIV with alcohol dependence." (PMID 24069309, 2013).
autism (17 papers, 2010 to 2025). Persistent deficits in social interaction and communication and interaction as well as a markedly restricted repertoire of activity and interest as well as repetitive patterns of behavior. "We observed that a higher abundance of CD4+ TEM2 cells correlates with the Autism Diagnostic Observation Schedule (ADOS) scores, suggesting a potential pathophysiological role in ASD." (PMID 41383128, 2025). "This supports the reporting of allergic problems and family history of autoimmunity as risk factors for ASD since lower numbers of CD4+ CD25 high Tregs are seen in individuals with autism." (PMID 35328471, 2022). "A significant increase in CD4+ memory and decrease in CD4+ naïve T cells associated with HLA A2-DR11 have also been observed in autism, as well as an imbalance of cytokines produced by CD4+ and CD8+ T cells with reported skewing toward Th2 response." (PMID 35328471, 2022). "In addition, increased CXCR7 expression on CD4+ T cells was associated with immune dysregulation in children with autism." (PMID 29560468, 2018). "They identified monocytes, neutrophils, and CD4+ T cells as potential sources of these elevated cytokines in autism." (PMID 39337983, 2024). "In contrast, our review identified elevated production of IFN-γ in in vitro stimulated CD4+ T cells and NK cells in the basal state in autism." (PMID 36268027, 2022). "From the studies we included, we identified neutrophils and CD4+ T cells as potential sources of IL-17 in the steady state of autism, in addition to IL-17 production by stimulated CD4+ T cells." (PMID 36268027, 2022). "Altogether, we suggest that monocytes are the predominant cells contributing to the elevated cytokine levels of IL-6, TNF-α, and IL-1β in autism, along with CD4+ T cells, which act as another source of IL-1β, whereas neutrophils are another source of IL-6." (PMID 36268027, 2022). "We also identified monocytes, neutrophils, and CD4+ T cells as potential sources of these elevated cytokines in autism." (PMID 36268027, 2022). "Studies on PBMCs and CD4+ T cells consistently showed differential responses from these cells in autism when stimulated with PMA/ionomycin and anti-CD3/CD28, respectively, as compared with the control group." (PMID 36268027, 2022). "Upregulation of intracellular enzymatic antioxidants of CD4+ T cells in autism children was revealed by a study, displaying the potential of oxidants to reduce IL-17A levels." (PMID 35844577, 2022). "Dysregulation of HLA-DR, Helios, IL-16 and CXC and CC chemokine receptors on CD4+ T cells is also involved in immune dysfunction of autism." (PMID 35844577, 2022). "We reviewed autism studies that investigated cytokine production by in vitro stimulated blood immune cells and identified monocytes, neutrophils, CD4+ T cells, and NK cells as the major cellular sources of these altered cytokines." (PMID 36268027, 2022). "Upon stimulation, there was a greater decrease in intracellular GSH and GSH/GSSG in both CD4 T cells and monocytes from children with autism compared to control children." (PMID 22928106, 2012). "Interestingly, the increase in IL-6, IL-17, TNF-α, and IL-1β in the serum was in accordance with the elevated levels of these cytokines in in vitro stimulated neutrophils, monocytes, and CD4+ T cells in individuals with autism, as compared with controls." (PMID 36268027, 2022). "In addition, IL-1β levels are markedly increased in post-stimulated monocytes and CD4+ T cells in autism." (PMID 36268027, 2022). "Thus, the more oxidized GSH/GSSG redox state of the intracellular glutathione pool in PBMCs and in activated CD4 T cells observed in children with autism would suggest a hyporesponsive phenotype that is less conducive to T-cell activation and proliferation." (PMID 22928106, 2012). "Therefore, the use of PMA/Ionomycin and anti-CD3/CD28 to stimulate PBMCs and CD4+ T cells, respectively, may represent a good model for studying cytokine production in autism." (PMID 36268027, 2022).
autism (continued). "The frequency of CD3+ T cells and their subsets, CD4+ and CD8+ cells, as well as the frequency of monocytes, B cells, and NK cells were comparable between subjects with autism and controls." (PMID 36268027, 2022). "We investigated the influence of 5-AIQ-treatment in BTBR T+ Itpr3tf/J (BTBR) mice as an autism model and used flow cytometry to assess the effect of 5-AIQ on FOXP3, Helios, GATA3, IL-9, IL-10 and IL-17A production by CXCR6+ and CD4+ T cells in the spleen." (PMID 33671196, 2021). "They found an imbalance between Th1 and Th2 cytokines with increased IL-4+CD4+ T cells and IL-4+CD8+ T cells and decreased proportions of IFN-γ+CD4+ T cells, IL-2+CD4+ T cells, and IFN-γ+CD8+ and IL-2+CD8+ T cells in children with autism." (PMID 29307081, 2018). "Both the CD4:CD8 ratio and CD4% have been shown to correlate with performance on the Autism Behavior Checklist, indicating a link between immunological function and phenotypic presentation." (PMID 25887094, 2015). "Additionally, cytokines such as IFN-γ, TGF-β, RANTES, and CXCL8 were also elevated in the plasma/serum of subjects with autism, with IFN-γ likely produced by CD4+ T cells and natural killer (NK) cells." (PMID 39337983, 2024). "Additionally, the levels of IL-6 and IL-17, but not TNF-α and IL-1β, were consistently higher in the unstimulated neutrophils, monocytes, and CD4+ T cells in autism subjects, as opposed to the controls." (PMID 36268027, 2022). "In mitogen-stimulated CD4 T cells from children with autism, the intracellular GSH concentration was ∼33% lower, the GSH/GSSG was ∼40% lower (P < 0.001), and the percent oxidized glutathione was ∼55% higher than in stimulated CD4 T cells from control children (<0.001)." (PMID 22928106, 2012).